PRUNE2 (prune homolog 2 with BCH domain)
Description:
May play an important role in regulating differentiation, survival and aggressiveness of the tumor cells.
Synonyms: BMCC1; BNIPXL; C9orf65; KIAA0367; A214N16.3; bA214N16.3
Tractability: No criterion of Open Targets' tractability assessment is met for any kind of drug.
Gene: Protein-coding gene on chromosome 9 (76,611,376 to 76,906,591, reverse strand). Ensembl gene ENSG00000106772.
Subcellular location: Cytoplasm
Subcellular location (Human Protein Atlas): Cytosol
Gene Ontology:
Molecular function: protein binding; pyrophosphatase activity
Biological process: apoptotic process
Cellular component: cytoplasm; glutamatergic synapse; presynapse
Genetic constraint (gnomAD): Loss-of-function variants: 129 observed, 216.71 expected, observed/expected ratio (o/e) 0.6, 90% interval 0.51 to 0.69. The upper end of that interval is the gene's LOEUF score, 0.69, which puts it in group 2 of 6, group 1 being the genes least tolerant of losing a copy. Missense variants: 3,218 observed, 3,576.7 expected, observed/expected ratio (o/e) 0.9, 90% interval 0.87 to 0.93. Synonymous variants: 1,212 observed, 1,316 expected, observed/expected ratio (o/e) 0.92, 90% interval 0.88 to 0.97.
Homologues: Orthologues: chimpanzee PRUNE2 (99% identical), macaque PRUNE2 (93% identical), dog PRUNE2 (75% identical), rabbit PRUNE2 (75% identical), guinea pig PRUNE2 (71% identical), mouse Prune2 (68% identical), tropical clawed frog prune2 (29% identical), rat Prune2 (10% identical), zebrafish prune2 (7% identical), Drosophila melanogaster CG11593 (5% identical). Paralogues in human: ATCAY (7% identical), BNIP2 (6% identical), BNIPL (4% identical).
Diseases named in the same sentence as PRUNE2 in open-access papers:
PRUNE2 is named in the same sentence as 44 diseases in open-access papers, as found by Europe PMC text mining. Sharing a sentence is not in itself a finding about the gene and the disease. The quoted sentences say what the papers report.
prostate carcinoma (20 papers, 2009 to 2025). A carcinoma that arises from epithelial cells of the prostate gland. "Of note, a recent study found PRUNE2 germline mutations in 2.8% of patients with familial prostate cancer, proposing PRUNE2 as a new prostate cancer predisposition gene." (PMID 36900197, 2023). "PRUNE2 was recently known to be expressed in melanoma and prostate cancer in which it is associated with AP2 protein involved in vesicle trafficking." (PMID 27641066, 2017). "According to the literature, germline mutations of the PRUNE2 gene have been very scarcely investigated in other forms of cancers, despite somatic mutations playing a role in the pathogenesis of prostate cancer, leiomyosarcoma, and colorectal cancer among others." (PMID 36900197, 2023). "Here, we described consistently lower expression of PRUNE2 in prostate cancers of all grades and stages as compared to normal prostate." (PMID 36645410, 2023). "In prostate cancer, the evidence is limited and controversial: an early report found that PRUNE2 expression was upregulated in prostate cancer and metastases in a small number of samples, and was androgen-inducible in prostate cancer cells." (PMID 36645410, 2023). "The mechanistic dysregulation of PCA3 and PRUNE2 is observed across the spectrum of tumor grades and stages, suggesting that this is an early and stable molecular event in prostate cancer." (PMID 36645410, 2023). "We consistently observed increased expression of PCA3 and decreased expression of PRUNE2 in prostate cancer compared with the adjacent normal prostate across all tumor grades and stages." (PMID 36645410, 2023). "Here, we investigated the PCA3/PRUNE2 regulatory axis from early (tumorigenic) to late (biochemical recurrence) genetic events during human prostate cancer progression." (PMID 36645410, 2023). "Altogether, the findings in the current study provide additional support for our previous findings that PRUNE2 acts as a functional tumor suppressor gene in human prostate cancer." (PMID 36645410, 2023). "Taken together along with the well-documented specificity of PCA3 overexpression, our findings establish the PCA3/PRUNE2 regulatory axis as an attractive early molecular target candidate for intervention in the therapy of human prostate cancer." (PMID 36645410, 2023). "The findings in our present study are also consistent with the negative regulation of PRUNE2 by PCA3 in prostate cancer." (PMID 36645410, 2023). "Studies of Prune homolog 2 (PRUNE2) in normal stem cells weren’t well reported, yet it`s expression or silencing in prostate cancer cells decreased and increased cell proliferation, respectively." (PMID 36824368, 2023). "The assessment of PCA3 expression directly and specifically in tissue (as opposed to urine) is a novelty and a strength as our primary goal was the study of the PRUNE2/PCA3 regulatory axis in human prostate cancer." (PMID 36645410, 2023). "Concerning PRUNE2, this gene is up‐regulated in prostate cancer where it plays a role in post‐endocytic trafficking 5 and in metastasis." (PMID 27641066, 2017). "For example, PRUNE2 gene is over-expressed in prostate cancer and down-regulates Rho-A and Rho-C that are involved in actin polymerization and oncogenic transformation." (PMID 21909426, 2011). "Furthermore, previous research has reported PRUNE2 as a tumor suppressor that is negatively modulated by PCA3 in prostate cancer." (PMID 41186818, 2025). "The inverse correlation of PCA3 and PRUNE2 expression is consistent with our prior findings of a functional interplay between the two genes as part of a unique regulatory unit functioning at a single genetic locus in prostate cancer cells with PCA3 negatively downregulating PRUNE2 expression." (PMID 36645410, 2023).
prostate carcinoma (continued). "First, we present additional correlative evidence from two retrospective post-surgical primary prostate cancer cohorts in support of our experimental model of PCA3 as a dominant-negative oncogene and PRUNE2 as a tumor suppressor gene and for their co-regulation in human prostate cancer." (PMID 36645410, 2023). "Finally, we were not able to fully address the relationship of reciprocal gene expression of PCA3 and PRUNE2 to the outcomes of metastases and prostate cancer-specific deaths, again due to the relative paucity of these events." (PMID 36645410, 2023). "Overall, the findings support the mechanistic role of a tumor-specific molecular axis in which PCA3 acts as dominant-negative oncogene and PRUNE2 as a tumor suppressor gene in human prostate cancer and indicate that the interplay between these genes is dysregulated early in prostate cancer." (PMID 36645410, 2023). "Co-regulation of PRUNE2/PCA3 RNA editing was also confirmed in human prostate cancer specimens." (PMID 26437436, 2015). "For instance, in prostate cancer, Prostate cancer antigen 3 (PCA3), a lncRNA, can form a double-stranded RNA with PRUNE2 (a human homolog of the Drosophila prune gene) to attract ADAR1 binding and exert an editing effect to regulate PRUNE2’s level." (PMID 38233935, 2024). "For example, in human prostate cancer, the antisense intronic lncRNA PCA3 inactivates the tumor-suppressor gene PRUNE2 at the RNA level through an ADAR-mediated mechanism and promotes malignant cell growth." (PMID 36795564, 2023). "PRUNE2 is a tumor suppressor gene of particular significance shown in prostate cancer, where its expression is regulated by prostate cancer antigen 3 (PCA3), a non-protein coding gene located on the opposite DNA strand in an intron of PRUNE2." (PMID 36900197, 2023). "In prostate cancer cells, ADAR1 mediates the formation of prune homolog 2 with BCH domain (PRUNE2)/prostate cancer antigen 3 (PCA3) double-stranded RNA by regulating PRUNE2 and PCA3 levels via adenosine-to-inosine RNA editing." (PMID 37524814, 2023). "PRUNE2 has been reported to function as a tumor suppressor gene in prostate cancer, where prostate cancer antigen three (PCA3) regulates levels of PRUNE2 through formation of a PRUNE2/PCA3 double‐stranded RNA." (PMID 28881068, 2017). "In experimental models of human prostate cancer, PCA3 overexpression as well as PRUNE2 silencing accelerates the growth of tumor xenografts in vivo, while increasing cell proliferation, adhesion, and migration in vitro." (PMID 28751581, 2017). "The PCA3 lncRNA binds to the PRUNE2 pre-mRNA in prostate cancer cell lines (LNCaP and PC3), generating a double stranded RNA molecule and therefore regulating the expression of PRUNE2 at both mRNA and protein levels." (PMID 29203868, 2017). "We showed that ARHGAP21 silencing in LNCaP prostate cancer cells decreased PCA3 and androgen receptor (AR) transcriptional levels and increased prune homolog 2 (PRUNE2) coding gene expression, indicating effective involvement of ARHGAP21 in androgen-dependent tumor pathway." (PMID 38896642, 2024). "The findings presented here represent additional evidence for the functional reciprocal co-regulation of PCA3 and PRUNE2 in the setting of early tumorigenesis but not in late events in human prostate cancer." (PMID 36645410, 2023). "As compared with normal prostate, we found that prostate cancer showed consistent increased expression of PCA3 and consistent decreased expression of PRUNE2 in tumors across a broad range of pathological attributes (i.e., Gleason grades, scores, groups, and stages) in both patient cohorts." (PMID 36645410, 2023). "However, a subsequent study on a larger number of samples found that PRUNE2 expression either decreased or did not increase in aggressive prostate cancer, and that PRUNE2 expression was not androgen-inducible." (PMID 36645410, 2023).
prostate carcinoma (continued). "On the other hand, we have not detected any regulatory effects of PRUNE2/PCA3 in late genetic events such as prostate cancer progressing to biochemical recurrence, which includes the development of local tumor recurrence and/or the development of metastatic disease." (PMID 36645410, 2023).
neuroblastoma (7 papers, 2009 to 2025). Neuroblastoma (NB) is the most common solid, extracranial childhood tumor. "PRUNE2 plays a role in various tumors as a tumor suppressor, including prostate cancer, colorectal cancer, and neuroblastoma." (PMID 41323367, 2025). "Loss-of-function mutations have been described in several tumor types, including germline and somatic mutations in parathyroid cancer and somatic mutations in solid papillary carcinoma, while high expression of PRUNE2 protein correlates with favorable prognosis in neuroblastoma." (PMID 36645410, 2023). "In neuroblastoma cells, PRUNE2 interacts with the AKT pathway." (PMID 32283676, 2020).
colorectal cancer (3 papers, 2023 to 2025). A primary or metastatic malignant neoplasm that affects the colon or rectum. "Increased PRUNE2 protein levels are associated with a favorable prognosis in neuroblastoma and leiomyosarcoma and have also been associated with lower tumorigenic activity in colorectal cancer." (PMID 36900197, 2023). "Recent studies have also suggested PRUNE2 as a predictive and prognostic biomarker in ovarian, thyroid, colorectal cancers, and choriocarcinoma." (PMID 41186818, 2025).
gastrointestinal stromal tumor (3 papers, 2009 to 2025). "Notably, a robust two- gene classifier composed of OBSCN and PRUNE2 was found to differentiate between gastrointestinal stromal tumor (GIST) and leiomyosarcoma (LMS) with near-perfect accuracy in close to 100 patients tested." (PMID 19961616, 2009).
leiomyosarcoma (3 papers, 2013 to 2025). An uncommon, aggressive malignant smooth muscle neoplasm, usually occurring in post-menopausal women. "In this study, we identify a novel PRUNE2::NTRK2 gene fusion in leiomyosarcoma and myxofibrosarcoma patients." (PMID 41323367, 2025).
Alzheimer disease (2 papers, 2013 to 2025). A progressive, neurodegenerative disease characterized by loss of function and death of nerve cells in several areas of the brain leading to loss of cognitive function such as memory and language. "These four PRUNE2 isoforms may play crucial roles in Alzheimer’s disease and cancer." (PMID 23741331, 2013).
hippocampal atrophy (2 papers, 2009 to 2017). "PRUNE2 is a gene associated with response to amphetamine and hippocampal atrophy which is a quantitative trait for AD." (PMID 28742084, 2017). "Elucidating the roles of PRUNE2, MAGI2, ARSB and EFNA5 in the regulation of neurodevelopment, protein degradation, apoptosis and neuronal loss could enhance our understanding of hippocampal atrophy and AD." (PMID 19668339, 2009).
malignant parathyroid tumors (2 papers, 2023). "Recently, somatic mutations of the tumor suppressor gene PRUNE2 were found to be frequent in parathyroid cancer (PC)." (PMID 36900197, 2023). "As CDC73 mutations may underlie both benign and malignant parathyroid tumors with varying penetrance and phenotypes, one can, therefore, speculate that mutations of the PRUNE2 gene could also give rise to similarly varying parathyroid tumor phenotypes with similarly varying penetrance." (PMID 36900197, 2023).
Merkel cell carcinoma (2 papers, 2019 to 2023). "Others have shown evidence of inactivating PRUNE2 mutations in Merkel cell carcinoma and that the restoration of downregulated PRUNE2 in oral cancer suppresses tumor cell migration, further supporting the role of PRUNE2 as a tumor suppressor." (PMID 36645410, 2023).
oral cancer (2 papers, 2023 to 2025). "PRUNE2 may also regulate the JAK-STAT pathway, affecting cell motility in oral cancer." (PMID 41186818, 2025).
parathyroid carcinoma (2 papers, 2019 to 2023). "We identified PRUNE2 mutations in patients with parathyroid carcinoma, atypical parathyroid tumors, and adenomas." (PMID 36900197, 2023).
prostate adenocarcinoma (2 papers, 2015 to 2023). "(A) PCA3 and PRUNE2 expression in nonneoplastic prostatic glandular tissue and in prostatic adenocarcinoma in the TCGA cohort illustrating consistent gene expression differences between tumor (n=497) and nonneoplastic (n=52) prostate in both cohorts." (PMID 36645410, 2023).
breast tumor (1 paper, 2025). "However, further studies are needed to identify PRUNE2 function in breast tumor pathogenesis." (PMID 41186818, 2025).
glioblastoma (1 paper, 2017). The most malignant astrocytic tumor (WHO grade IV). "To analyse the role of KLRC3, CHI3L1 and PRUNE2 genes in the migration ability of glioblastoma cells we used a matrigel invasion chamber system." (PMID 27641066, 2017). "In the present study, the effect of KLRC3 extinction is compared to those of the two other genes CHI3L1 and PRUNE2 in a human glioblastoma cell line." (PMID 27641066, 2017). "Three genes named CHI3L1,KLRC3 and PRUNE2 were found overexpressed in glioblastoma undifferentiated cells (related to CSC) compared to the differentiated ones." (PMID 27641066, 2017). "To determine the putative role of CHI3L1, KLRC3 and PRUNE2 genes in glioblastoma aggressiveness, we have assessed the three shRNA cell lines tumourigenic potential." (PMID 27641066, 2017). "Based on our previous study describing an overexpression of three glycosylation‐related genes, KLRC3, CHI3L1 and PRUNE2 in glioblastomas undifferentiated cells related to CSC, we assessed whether these genes are closely linked to glioma tumourigenesis mechanisms." (PMID 27641066, 2017). "Although silencing of CHI3L1, KLRC3 and PRUNE2 decrease cell proliferation, migration, clonogenicity and tumourigenesis, our results demonstrate that KLRC3 is of prime importance for glioblastoma cells aggressiveness and their ability to promote cancer progression." (PMID 27641066, 2017).
head and neck cancer (1 paper, 2022). A primary or metastatic malignant neoplasm affecting the head and neck. "Aberrant expression and methylation of PRUNE2 are reportedly associated with EMT process and nodal metastases in head and neck cancer (HNSC)." (PMID 36137089, 2022).
lung carcinoma (1 paper, 2022). "Notably, a variant of PRUNE2 was identified in the remodelling areas of COPD patients, and approximately 10% of lung cancer patients were affected by a mutation of PRUNE2." (PMID 35885019, 2022).
parathyroid neoplasms (1 paper, 2023). "Here, we report novel, rare PRUNE2 mutations located in exons 3, 8, 9, and 12 in patients with parathyroid tumors in the genetically homogenous Finnish population." (PMID 36900197, 2023). "The germline mutation status of PRUNE2 was investigated in a large cohort of patients with parathyroid tumors from the genetically homogenous Finnish population, 15 of which had PC, 16 atypical parathyroid tumors (APT), and 6 benign parathyroid adenomas (PA)." (PMID 36900197, 2023). "Recently, PRUNE2 mutations were indicated in the pathogenesis of aggressive parathyroid neoplasms." (PMID 36900197, 2023). "While further research is needed, mutations of the PRUNE2 gene could play a role in the pathogenesis of parathyroid tumors." (PMID 36900197, 2023). "Still, the frequent finding of rare germline mutations of PRUNE2 may point to the gene playing a role in the pathogenesis of parathyroid neoplasms." (PMID 36900197, 2023). "Rare germline PRUNE2 variants are frequent in Finnish patients with parathyroid neoplasms, regardless of tumor type (PC, APT, or PA)." (PMID 36900197, 2023). "Further studies are needed to clarify the role of PRUNE2 in patients with parathyroid tumors." (PMID 36900197, 2023). "In this study, we report that Finnish PHPT patients with CDC73 mutation-negative parathyroid tumors frequently display rare germline mutations in the PRUNE2 tumor suppressor gene." (PMID 36900197, 2023).
Sepsis (1 paper, 2021). Sepsis is defined as life-threatening organ dysfunction caused by a dysregulated host response to infection. "Hence, PRUNE2 might participate in sepsis through regulating Rho signaling and Rho kinase." (PMID 34772470, 2021). "Although there are no direct evidences on the relationship between G0S2, PRUNE2, SLC22A4 and septic shock or sepsis, several researches indicated their indirect association." (PMID 34772470, 2021).
Turner syndrome (1 paper, 2023). Turner syndrome is a chromosomal disorder associated with the complete or partial absence of an X chromosome. "APT patient 152142 with Turner syndrome, who was 59 years old at the time of her diagnosis, had three different germline PRUNE2 variants; however, only (c.1784G > T, p.Ser595Tyr) was predicted to be damaging." (PMID 36900197, 2023).